MMP9 (matrix metallopeptidase 9)
Diseases named in the same sentence as MMP9 in open-access papers (continued):
Sharing a sentence is not in itself a finding about the gene and the disease.
melanoma (continued). "Transcriptome analysis revealed significant upregulation of MMP-9 and Madcam1 in melanoma cells exposed to TRIM59-/--M2 CM." (PMID 31600735, 2019). "MMP-2 and MMP-9 are especially relevant in melanoma progression, since they play an important role in tumor development, growth, angiogenesis, and metastasis." (PMID 30147443, 2018). "Among all MMPs, MMP9 is particularly important for melanoma progression, and increased expression and activity of these MMPs were observed in invasive melanoma cell lines." (PMID 30241392, 2018). "MMP-9 concentration at baseline in serum of 28 patients with melanoma according to socio-demographic, clinical characteristics and molecular features." (PMID 30154717, 2018). "In particular, a fundamental role is played by Matrix Metalloproteinase 9 (MMP-9) that promoted melanoma invasiveness and spreading via the degradation of several components of the extracellular matrix." (PMID 30154717, 2018). "In the current study, we found that in two melanoma cell lines, A2058 and A375, uPA, TIMP-1, MMP-2 and MMP-9 were associated with cell migration and invasion." (PMID 30042328, 2018). "MMP-9 serum levels were evaluate in melanoma samples according to socio-demographic, clinical and molecular features, including the presence of circulating-free DNA BRAFV600E mutation." (PMID 30154717, 2018). "Previously it was proved that silymarin decreased the expression of MMP-2 and MMP-9 in human melanoma cells, having beyond the protective action of hepatocytes an anticancer potential." (PMID 30150935, 2018). "Validation of in vitro data were assessed in peripheral blood samples from melanoma patients analyzing MMP-9 levels according to the presence of circulating-free DNA BRAFV600E mutation." (PMID 30154717, 2018). "CAFs exhibit increasing expressions and secretion of VEGFa, FGF2, and MMP9, promoting proliferation, migration, and tube formation of ECs, and melanoma angiogenesis." (PMID 30285793, 2018). "ELISA and Real-Time PCR analyses showed that MMP-9 was statistically down-regulated (p < 0.05) in A375 and A2058 melanoma cell lines after treatment with dabrafenib for 48 h." (PMID 30154717, 2018). "Oral administration of daphnane diterpenes-rich Thymelaea hirsuta extract (TH) suppressed MMP2 and MMP9 expression, decreasing lung tumor in mice injected with B16 murine melanoma cells." (PMID 30157785, 2018). "It was found that GBEE inhibited the growth and pulmonary metastasis of B16-F10 melanoma transplanted tumor and downregulated the level of MMP-9 protein." (PMID 30046339, 2018). "Further studies, including a larger series of melanoma patients, are needed to better clarify the impact of MMP-9 as a marker of response to treatment with BRAF inhibitors." (PMID 30154717, 2018). "On these bases, in the present study functional experiments were performed using melanoma cell models to confirm the correlation between MMP-9 expression and MAPK pathway modulation during the treatment with BRAF inhibitors." (PMID 30154717, 2018). "Previous investigations have shown significant correlations of TIMPs and uPA with the physiological activities of MMP-2 and MMP-9 and their involvement in the invasiveness, metastasis, and prognosis of melanoma." (PMID 30042328, 2018). "The performed analyses showed that MMP-9 and pEKR1-2 were statistically down-regulated in melanoma cells after treatment with dabrafenib." (PMID 30154717, 2018). "Together, our data showed a promoting effect of 10h on B16/F10 melanoma cell motility, invasion, and MMP9 expression, all critical characteristics for melanoma progression and metastasis." (PMID 30241392, 2018). "Previous studies showed that KLK7 also cleaved pro‐MMP9 generating active MMP9, and uPAR, two members of key proteolytic systems in melanoma invasion." (PMID 28636767, 2017). "LIN28 is a specific, post-transcriptional inhibitor of let-7 biogenesis; let-7b overexpression suppresses MMP9 expression in melanoma cells." (PMID 28587210, 2017).
melanoma (continued). "High microenvironmental pressures increased MMP-2 and MMP-9 expression in melanoma cells, induced ECM remodeling and VM channel formation and accelerated tumor cell invasion." (PMID 27034014, 2017). "In a murine model, after Flt3L-expressing B16 melanoma cells were injected into mice, it induced dendritic cell expression of MMP-9, which in turn reduced fibrosis." (PMID 28902848, 2017). "CD44 forms a complex with MMP9, which results in the activation of actomyosin contractility in melanoma." (PMID 28085224, 2017). "Acidic extracellular pH (pHe) has been found to increase intracellular Ca2+ and matrix metalloproteinase-9 (MMP-9) expression by activating NF-κB in the mouse B16 melanoma model." (PMID 29108231, 2017). "We have found that acidic extracellular pH (pHe) induces the production of matrix metalloproteinase-9 (MMP-9), the activity of which correlated with the metastatic ability of mouse B16 melanoma variants." (PMID 29108231, 2017). "We previously reported that acidic pHe induces MMP9 production in mouse B16 melanoma cells and cell invasion through type IV collagen sheets, as well as activating intracellular signaling pathways." (PMID 29108231, 2017). "And although direct RNA–DNA binding has not been shown, lncRNA SLNCR1 is required for bringing androgen receptor to the MMP9 promoter, which increases MMP9 expression and leads to melanoma invasion." (PMID 28747406, 2017). "Mutation of the TRAF6 ubiquitination sites in BSG blocks its ability to induce MMP-9 expression and reduces melanoma cell invasion." (PMID 27791197, 2016). "Expression of MMP-2 and MMP-9 has also been shown to promote cell invasion and metastasis of melanoma." (PMID 26517521, 2016). "The transcript levels of MMP9 in the samples analyzed in GSE31879 melanoma dataset were about 1.5 fold higher in melanoma samples compared to melanocyte controls (p<0.01)." (PMID 27115178, 2016). "Next, we examined the effect of CoQ0 on the targets of β-catenin, cyclin D1, survivin, and MMP-9 by immuhistochemicals analysis of B16F10 melanoma xenografted tumor tissues." (PMID 26968952, 2016). "On these bases, we first performed computational analysis to assess the methylation patterns of MMP9 gene in melanoma samples according to mRNA expression." (PMID 27115178, 2016). "CD44-binding matrix metalloproteinase 9 (MMP9) favors melanoma amoeboid migration and actomyosin contractility." (PMID 27308633, 2016). "Computational analysis revealed DNA hypermethylation within the intragenic CpG-2 region of MMP9 gene in melanoma samples with high MMP-9 transcript levels." (PMID 27115178, 2016). "Accordingly, our in vitro experiments demonstrated that MMP9 CpG-2 methylation hotspot was correlated with higher transcript and protein levels of MMP-9 in melanoma cell lines." (PMID 27115178, 2016). "The gelatinases, MMP-2 and MMP-9, primarily cleave collagen type IV and are believed to play a crucial role in the progression of melanoma cells." (PMID 27271600, 2016). "Melanoma was used as tumor model to investigate the relationship between the DNA intragenic methylation of MMP9 gene and MMP-9 overexpression at transcriptional and protein levels." (PMID 27115178, 2016). "The degradation of pericellular and stromal compartments, mainly mediated by MMP-9, is an essential process during melanoma invasion and migration." (PMID 27115178, 2016). "MMPs, specifically MMP-2 and MMP-9, are well characterized for their key roles in tumor progression, cell migration and invasion of cancers including melanoma." (PMID 26760964, 2016). "Melanoma cells derived from Wnt, acting through Fz receptors, induce MMP-9 and MMP-2 expression, which plays a vital role in cell migration and invasion." (PMID 26968952, 2016).
melanoma (continued). "It was found that treatment of honokiol, NAC and DPI reduced the expression of MMP-2 and MMP-9 in Hs294t and SK-Mel28 melanoma cells, thus suggesting a common mechanism of action by these agents." (PMID 26760964, 2016). "Only few publications concerned the evaluation of the concentrations of MMP-2 and MMP-9 in serum of patients with melanoma." (PMID 26002577, 2015). "The melanoma lines showed highly different invasion patterns, and differences in invasiveness was associated with differences in expression of MMP-2 and MMP-9." (PMID 26667022, 2015). "The anti-melanoma effects of aloe-emodin included time dependent anti-proliferation and inhibition of MMP-9." (PMID 25102117, 2014). "Using mouse metastatic B16 melanoma cells, we found that acidic pHe induces cellular expression of matrix metalloproteinase-9 (MMP-9) and induces morphological changes to a fibroblastic phenotype." (PMID 25493076, 2014). "In fact, we show here that the IGFBP-3 content of melanomas and their tissutal environment becomes progressively lower with advancing disease, and that IGFBP-3 loss is accompanied by a parallel increase in MMP-9." (PMID 24905466, 2014). "Monoclonal antibodies against MMP-2 and MMP-9 were also included in this experiment because both have a role in melanoma development." (PMID 24788523, 2014). "We have reported that induction rate of MMP-9 secretion correlates with metastatic potential of mouse B16 melanoma clones, and an acidic pHe stimulates invasion through a type-IV collagen barrier." (PMID 24004445, 2013). "In human melanoma models, an acidic pHe increases both migration and invasiveness in vitro, accompanied by MMP-9 activation." (PMID 24004445, 2013). "Chen and colleagues analyzed samples from patients and reported that there is a differential expression of MMP-9, which is present in early stage of benign lesions and a significant increase occurs in advanced malignant melanoma stages." (PMID 23342114, 2013). "For example, treatment with the MSA paclitaxel impaired secretion of MMP-2 and MMP-9 and significantly reduced the invasion of melanoma cells." (PMID 23631818, 2013). "In MMP-9-deficient mice, the number of metastatic colonies of B16-BL6 melanoma cells or Lewis lung carcinoma cells fell significantly when compared with normal mice." (PMID 24039823, 2013). "Such an inhibitory effect of NOV on MMP-9 expression is consistent with previous studies showing that NOV overexpression in Ewing's sarcoma and melanoma cells leads to repression of MMP-9." (PMID 22353423, 2012). "MMP-9 expression in melanoma cells was found exclusively during the horizontal growth phase but not during the vertical phase." (PMID 20631829, 2010). "Recent evidence has shown that expression levels of the GEF RasGRF1 regulate constitutive MMP-9 production in human melanoma cells." (PMID 19678938, 2009). "RasGRF1 specifically activates H-Ras, but not other Ras homologs in vivo, and RasGRF1 activation of H-Ras induces constitutive MMP-9 production in human melanoma cells." (PMID 19678938, 2009). "This study does not provide strong evidence for further investigation into the role of the MMP-9 SNPs in melanoma progression." (PMID 17346338, 2007). "Moreover, 22‐HTG induced apoptosis and suppressed melanoma cell invasiveness by inhibiting MMP‐9 activity and MAPK signalling pathways." (PMID 41546170, 2026). "Immunofluorescence and western blot analysis confirmed reduced MMP‐2 and MMP‐9 protein expression and an increased Bax/Bcl‐2 ratio following emodin treatment, which indicates emodin's potential as a therapeutic option for highly metastatic melanoma." (PMID 41546170, 2026). "Vimentin is a key EMT biomarker present in mesenchymal cells and usually overexpressed during cancer metastasis, while MMP-2 and MMP-9 are peptidases involved in extracellular matrix remodeling and tumor invasive processes, favoring melanoma spreading and metastasis." (PMID 39981176, 2025).
melanoma (continued). "Moreover, in melanoma cells, the rapamycin-insensitive companion of mTOR complex 2 (Rictor-mTORC2) can phosphorylate AKT, causing overexpression of MMP-2 and MMP-9 and microvessel formation." (PMID 39866233, 2025). "CAF-derived MMP-9 may contribute to resistance against anti-PD-1 therapy by cleaving PD-L1 from melanoma cell surfaces, potentially impairing immune system recognition." (PMID 40399946, 2025). "Additionally, miR-450b was overexpressed in canine melanoma metastatic cells, resulting in an increased matrix metalloproteinase-9 (MMP9) expression (which is required for tumor metastasis) and the suppression of bone morphogenetic protein-4 (BMP4)." (PMID 41227463, 2025). "Furthermore, non-VEGF-driven intussusceptive angiogenesis, observed in human melanoma metastases with high MMP-9 expression and immune cell infiltration near intravascular pillars, is rare in mouse patient-derived xenografts (PDXs)." (PMID 40284474, 2025). "A similar increase in MMP9 expression was noted in B16F10 melanomas and LLC1 tumors." (PMID 38441970, 2024). "TMZ-induced MMP9 activity in our study may not be enough for gelatinase activity compared to some cells (eg, melanomas, squamous cell carcinomas) possesing high MMP9 basal level." (PMID 38906916, 2024). "MMP-2 and MMP-9 are involved in angiogenesis and melanoma cell invasiveness." (PMID 38794128, 2024). "Additionally, MMP9 is a crucial regulator implicated in ESCC outcome and prognosis, and its expression can be regulated by GLI2 in melanoma cells." (PMID 38924029, 2024). "Additionally, related to non-tuberculous mycobacteria, heat-killed Mycobacterium indicus pranii has been shown to inhibit melanoma cell invasion by reducing MMP-9 expression." (PMID 39684712, 2024). "In addition, the lncRNA SLNCR1 increases melanoma invasion by transcriptionally upregulating matrix metalloproteinase 9 (MMP9) through cooperation with brain-specific homologous box protein 3a (Brn3a) and the androgen receptor (AR)." (PMID 39060946, 2024). "Quercetin decreased pro-MMP-9 via the PKC route to prevent murine melanoma B16-BL6 cell invasion." (PMID 38398617, 2024). "Regarding modulations of MMPs and angiogenesis as the important molecular targets for the anti-metastatic action of apigenin, MMP2 in melanoma cells and MMP9 in melanoma and ovarian cancer cells, and vascular cell adhesion protein 1 (VCAM-1) in B16-BL6 melanoma cell were regulated." (PMID 38515580, 2024). "MMP9, for instance, has demonstrated a critical role in driving tumor progression and metastasis, notably in triple-negative breast cancer and the early stages of melanoma." (PMID 38939095, 2024). "Moreover, the conditioned medium from melanoma CSCs promoted ROS production, cytokines and MMP-9 secretion and NET release from neutrophils." (PMID 39199632, 2024). "Moreover, it has been observed that tryptanthrin reduced melanoma metastasis and angiogenesis by a decrease in matrix metalloproteinase 9 (MMP-9) and VEGF, respectively." (PMID 39684513, 2024). "Interestingly, Mw downregulated MMP-9 expression in the highly invasive B16F10 melanoma model, which was sensitive to Mw treatment." (PMID 39534596, 2024). "Indeed, high levels of MMP-9 have been described in melanoma patients and its expression has been suggested to be a tumor progression marker." (PMID 38247872, 2024). "Mw has been shown to downregulate MMP-9 in melanoma, inhibition invasion." (PMID 39534596, 2024). "Finally, the HDAC6/PTPN1/ERK1/2 axis leads to an increase in matrix metallopeptidase 9 (MMP9), leading to melanoma metastasis." (PMID 39199614, 2024). "Additionally, due to its inhibitory effects on the production of VEGF, MMP-2, MMP-9, and nitric oxide, ursolic acid act as a potent anti-angiogenic member in melanoma." (PMID 37803407, 2023).
melanoma (continued). "One study reported that TRAIL could interact with DR5 and activate the NF‐κB pathway in B16F10 (mouse melanoma cells), and then induced MMP‐9 that can promote tumor proliferation and lung metastasis in vivo." (PMID 37879960, 2023). "The spindle-shaped morphology could also point to an endothelial-to-mesenchymal transition (EndMT), which has been reported for melanoma-derived sEVs and also as a result of MMP-9 stimulation within the endothelial cells." (PMID 37226100, 2023). "MMP2 and MMP9 could be released in proximity of the contact regions also by the small exoplasmic vesicles observed on protrusions of melanoma cells." (PMID 37371639, 2023). "Correctively, LL-37-induced CXCL5, IL-23p19, MMP-1 and MMP-9 could promote angiogenetic activity in melanoma tumor microenvironment, leading to the local invasion of melanoma which contributes to T stage in melanoma patients." (PMID 36980564, 2023). "Furthermore, these authors observed that the immunohistochemical heterogeneity of LAM cells was associated with different patterns; for example, larger LAM cells stained more strongly for MMP-2, MMP-9, and Human Melanoma Black-45 monoclonal antibody." (PMID 36817769, 2023). "In another study, the exposition of murine melanoma B16-BL6 cells to quercetin resulted in the significant inhibition of the cell invasion and migration associated with the suppressed gelatinolytic activity of MMP-9 and PKC signaling." (PMID 37687080, 2023). "Correctively, LL-37-induced CXCL5, IL-23p19, MMP-1 and MMP-9 could promote angiogenetic activity in melanoma, leading to the local invasion of melanoma which contribute to T stage in melanoma patients." (PMID 36980564, 2023). "Some of these mediators, such as MMP-9 and GM-CSF, are predictors of melanoma progression." (PMID 37525065, 2023). "Exosomes from activated CD8+ T cells were shown to activate the ERK and NF-κB pathways in melanoma cells, leading to melanoma metastasis in vivo by increasing the expression of MMP9 via Fas signaling, suggesting a role for CD8+ T cell-derived exosomes in tumor immune escape." (PMID 37153615, 2023). "Finally, in a cohort of stage IV melanoma patients, we found increased circulating levels of neutrophil-related mediators, such as MMP-9, MPO, GM-CSF and CXCL8/IL-8, as well as increased levels of NET biomarkers, compared to healthy controls." (PMID 37525065, 2023). "Next, we evaluated whether Bcl2L10was able to affect the activity of matrix metalloproteinases MMP2 and MMP9,which we previously demonstrated to be modulated by Bcl-2 and Bcl-xL in melanoma." (PMID 36046354, 2022). "In addition, previous studies have found that MMP9 is activated during the invasion of melanoma cells." (PMID 36387162, 2022). "In melanoma, upregulation of matrix metalloproteinases (MMPs) is associated with migration of the tumor, and upon treatment of B16F10 cells with NPC-402, it dose-dependently downregulates the expression of MMP1 and MMP9 compared to untreated." (PMID 35982963, 2022). "MMP9 mRNA levels were also higher in metastatic than in primary melanoma." (PMID 35589683, 2022). "MMP9 has also been considered as an indicator of invasiveness in malignant melanoma and a marker of treatment by BRAF (B-Raf proto-oncogene, serine/threonine kinase) inhibitors, a common genetic mutation in melanoma." (PMID 36452505, 2022). "Furthermore, inhibition of MMP9 expression decreases the tumor-promoting function of TAMs in melanoma." (PMID 35409404, 2022). "Interestingly, MMP9, a metalloproteinase responsible for BM breakdown in tumor invasion, showed a slight downregulation in the melanoma RF-FTMs compared to that in the PF-FTMs and little difference was found between the two types of HNSCC FTMs." (PMID 36232952, 2022). "Indeed, CD8+ T cell–derived exosomes are reported to promote invasion of melanoma and lung cancer cells by increasing the expression of MMP9 via Fas signaling in the malignant cells." (PMID 36970719, 2022).